IL3 (interleukin 3)
Diseases named in the same sentence as IL3 in open-access papers (continued):
Sharing a sentence is not in itself a finding about the gene and the disease.
anaphylaxis (2 papers, 2017 to 2023). An acute hypersensitivity reaction that occurs from exposure to an allergen. "Systemic increases in tryptase and IL-3 were also detected during reactions, providing supporting biochemical evidence of anaphylaxis." (PMID 37402149, 2023). "This suggests that it is unlikely that basophil migration during anaphylaxis is related to changes in basophil development or homeostasis, a process that is IL-3 elicited for basophils that operate in an IgE-dependent manner or TSLP elicited for basophils that operate in a non–IgE-dependent manner." (PMID 28342911, 2017). "Our results are consistent with those of a recent study that demonstrated no changes in CCL11 or IL-3 levels during anaphylaxis." (PMID 28342911, 2017).
Arthritis (2 papers, 2014 to 2022). Inflammation of a joint. "The affected 5q LOH interval harbors several cytokine genes (including IL-3, IL-4, IL-5, IL-13, and CSF2), a gene associated with arthritis susceptibility (SLC22A4), a DNA repair gene (RAD50), and a gene that promotes Type 1 interferon responses (IRF1)." (PMID 25107306, 2014). "The levels of IL-3, IL-5, IL-9, and LIF, as well as those of GM-CSF and VEGF, did not increase in the setting of CFA-induced arthritis." (PMID 36293292, 2022).
atopic asthma (2 papers, 2013 to 2014). An asthma that is characterized by symptoms that are triggered by an allergic reaction caused by inhaled allergens such as dust mite allergen, pet dander, pollen and mold. "Atopic asthma is a typical IgE-mediated disease in which the enhanced production of IgE is driven by the activation of Th2 cells, which release a distinct pattern of cytokines, including interleukin 4 (IL4) and IL3, in response to specific antigen presentation." (PMID 23521807, 2013).
B-cell lymphoblastic leukemia (2 papers, 2024 to 2025). "In studies, patients with B-cell lymphoblastic leukemia following CAR-T cell therapy presented elevated levels of IL-1α, IL-2, IL-3, IL-5, IL-6, IL-8 IL-10, IL-15, IFN- γ, procalcitonin, CRP, G-CSF, GM-CSF, and MCP-1, and their levels were linked to the severity of neurotoxicity." (PMID 39409959, 2024).
bladder cancer (2 papers, 2019 to 2023). "A previous study reported that IL3 mediates miR-145 biogenesis and enhances the development of cancer stem cells in bladder cancer." (PMID 31619200, 2019).
brain ischemia (2 papers, 2007 to 2012). Diminished or absent blood supply to the brain caused by obstruction (thrombosis or embolism) of an artery resulting in neurologic damage. "IL-3 also attenuated neuronal damage caused by free radicals, which are known to be overproduced during and after brain ischemia." (PMID 17915029, 2007).
capillary leak syndrome (2 papers, 2020 to 2022). A syndrome characterized by leakage of intravascular fluids into the extravascular space. "However, the fusion protein tagraxofusp-erzs (formerly called SL-401), which consists of the ligand IL3 fused to a truncated diphtheria toxin, has been reported to cause capillary leak syndrome as a common side effect in more than 55% of patients." (PMID 33233768, 2020).
Crohn disease (2 papers, 2010 to 2012). A gastrointestinal disorder characterized by chronic inflammation involving all layers of the intestinal wall, noncaseating granulomas affecting the intestinal wall and regional lymph nodes, and transmural fibrosis. "The gene cluster on chromosome 5q31 harbors several immune related genes, including the interleukins IL3, IL5 and the interferon regulator IRF1, which have been associated with Crohn’s disease in the European population." (PMID 22606245, 2012). "Previous analyses of Crohn's disease describe an enrichment of pathways involved in calcium signaling, Transcription/ChREBP regulation, Immune response (IL2, IL3, IFN alpha/beta, antigen presentation), lipid metabolism, and the developmental role of CDK5 in neuronal development." (PMID 20584322, 2010).
degenerative disc disease (2 papers, 2014 to 2024). "The analysis revealed through macrogenetic research of intestinal flora that DHJSD may modulate TNF, NF-kappa B, PI3K-Akt, MAPK signaling pathways through CASP8, TNF-α, IL-3, and other crucial proteins to inhibit apoptosis in the nucleus pulposus and treat rat intervertebral disc degeneration." (PMID 39418241, 2024).
endothelial dysfunction (2 papers, 2023 to 2025). In vascular diseases, endothelial dysfunction is a systemic pathological state of the endothelium (the inner lining of blood vessels) and can be broadly defined as an imbalance between vasodilating and vasoconstricting substances produced by (or acting on) the endothelium. "IL-35 inhibits endothelial dysfunction directly, and IL-3 upregulates S100A8 expression in HUVECs in vitro experiments." (PMID 41155408, 2025).
eosinophilic diseases (2 papers, 2017 to 2018). "The three β-chain cytokines, IL-3, IL-5, and GM-CSF are all present in human eosinophilic diseases and have both highly redundant and yet critically unique roles in the EOS biology." (PMID 28971096, 2017).
fungal infection (2 papers, 2024). "Anti-inflammatory cytokines such as IL-3, IL-4, IL-5, IL-9, IL-10, and IL-13 were also induced within 3 h of fungal infection in all three groups of mice and remained high up to the 7th day period." (PMID 38783167, 2024).
Immunodeficiency (2 papers, 2018 to 2021). Failure of the immune system to protect the body adequately from infection, due to the absence or insufficiency of some component process or substance. "Only two questionnaires are linked to IL-3, the immunodeficiency disease questionnaire (ISAQ) and the immune functioning assessment questionnaire (IFQ); thus the hybrid magneto-based biosensor is the only biosensor that measures IL-3 and is paired with them." (PMID 34372196, 2021).
injury (2 papers, 2015 to 2025). Damage inflicted on the body as the direct or indirect result of an external force, with or without disruption of structural continuity. "The overlapping roles of cytokines, particularly IL-3, IL-6, IL-10, IL-17, TNF-α, and TGF-β, suggest significant crosstalk between pathways in radiation-induced lung injury (RILI) and immunotherapy-related lung injury (IRLI)." (PMID 40299683, 2025). "Notably, complement activation is associated with various organ injuries, including acetaminophen-induced liver injury, and CSF2RB is a high-affinity receptor for IL-3, IL-5, and colony-stimulating factor." (PMID 26335687, 2015).
ischemia (2 papers, 2020 to 2022). A hypoperfusion of the BLOOD through an organ or tissue caused by a PATHOLOGIC CONSTRICTION or obstruction of its BLOOD VESSELS, or an absence of BLOOD CIRCULATION. "A cytokine mixture of IL-3 and GM-CSF was administered to the ischemia model." (PMID 35968363, 2022). "In the ischemic brain, treatment with a cytokine mixture containing GM-CSF and IL-3 may be worth trying to prevent ischemia-induced secondary neurodegeneration." (PMID 35968363, 2022). "Several factors are reported to induce the translocation of GLUT1 to the plasma membrane, including interleukin 3 (IL-3), nitric oxide, low-density lipoprotein (LDL), insulin, dehydroepiandrosterone (DEHA), ischemia, and the combination of hypoxia and high glucose concentration." (PMID 32962633, 2020).
kidney tumor (2 papers, 2018 to 2022). "Moreover, TECs derived from differing tissues, including breast and kidney tumors, produce IL-3 and are dependent on IL-3 for their growth." (PMID 29238040, 2018). "IL-3 is a proinflammatory and proangiogenic cytokine mainly released by activated T lymphocytes and mast cells in the TME and acts as an autocrine factor for human breast and kidney tumour-derived endothelial cells." (PMID 36010912, 2022).
liver cancer (2 papers, 2019 to 2021). An epithelial or non-epithelial malignant neoplasm that arises from the liver. "LCN2 can modulate the apoptotic process by interacting with interleukin-3 (IL-3) and IL-8 to influence tumor progression, metastasis, and prognosis in FL5.12 cells, endometrial cancer, and liver cancer." (PMID 34903175, 2021).
liver fibrosis (2 papers, 2018 to 2021). "IL-3, IL-17 and IL-33 induce liver fibrosis through various mechanisms, therefore an approach targeting them as a major participant in the “fibrosis pathway” is expected to be worthwhile." (PMID 33841164, 2021). "It was reported that Th1 cytokines suppress liver fibrosis, with interferon-γ being a potent inhibitor of the activation of hepatic stellate cells, while Th2 cytokines such as IL-4 and IL-3 promote activation of hepatic stellate cells and progression of liver fibrosis." (PMID 30116748, 2018).
microcephaly (2 papers, 2021 to 2022). A congenital or acquired developmental disorder in which the circumference of the head is smaller than normal for the person's age and sex. "When the groups of neonates with microcephaly and controls were compared, we identified the top discriminant scores for IL-1β, IL-3, EOTAXIN (CCL11) and IL-12p70." (PMID 33875756, 2021). "Associated with other mediators such as IL-3, IL-1β; eotaxin was considered as a differential marker in children exposed in utero to ZIKV, born with or without microcephaly." (PMID 36146688, 2022). "In the canonical coefficient analysis between controls and those exposed to ZIKV without microcephaly, we found that IL-1β, IL-3, IL-4, IL-7 and EOTAXIN (CCL11) were the top CSF markers in our model." (PMID 33875756, 2021).
myocarditis (2 papers, 2019 to 2022). Myocarditis is a condition that is characterized by inflammation of the heart muscle (myocardium). "AAV9-IL9 showed remarkable enrichment over all other interleukins in both Pool 60 and Pool 15, and in combination with IL3, IL4, IL13, and IL15 (Pool 5), significantly improved CVB3-induced myocarditis." (PMID 35508525, 2022). "In this study, the pooled AAV9-mediated overexpression of 60 cytokines in a human Coxsackievirus-B3-induced myocarditis mouse model allowed the identification of five cardioprotective interleukins (IL9, IL3, IL4, IL13, and IL15)." (PMID 35508525, 2022).
Nephropathy (2 papers, 2019 to 2025). A nonspecific term referring to disease or damage of the kidneys. "Less-characterized interleukins such as IL-3, IL-5, IL-9, and IL-27 demonstrate dual or context-dependent roles, particularly in shaping immune tolerance and tissue-specific complications such as nephropathy and neuropathy." (PMID 40804870, 2025).
Parkinson disease (2 papers, 2011 to 2024). A progressive degenerative disorder of the central nervous system characterized by loss of dopamine producing neurons in the substantia nigra and the presence of Lewy bodies in the substantia nigra and locus coeruleus. "In this study, it is found that astrocytic IL‐3 and microglial IL‐3R are positively responsive to α‐synuclein pathology in the brains of transgenic A53T Parkinson's disease (PD) mice and in an adeno‐associated virus (AAV)‐human α‐synuclein (AAV‐hα‐Syn)‐injected PD mouse model." (PMID 39225429, 2024). "This study demonstrated that subcutaneous administration of a cytokine mixture of GM-CSF and IL-3 exhibited marked neuroprotective effects against 6-OHDA-induced Parkinsonism in rats." (PMID 22398979, 2011). "In this study, we found that subcutaneous injection of a cytokine mixture containing granulocyte macrophage colony-stimulating factor and interleukin-3 (IL-3) markedly suppressed dopaminergic neurodegeneration in 6-hydroxydopamine-lesioned rats, an animal model of Parkinson's disease." (PMID 22398979, 2011).
psychosis (2 papers, 2017 to 2025). "It was observed that the serum levels of IL-2 and IL-6 are increased in first episode drug-naïve patients with psychosis, and that IL-3 levels are significantly increased in patients with chronic schizophrenia." (PMID 26649857, 2017).
abortion (1 paper, 2019). the ending of pregnancy by removing a fetus or embryo before it can survive outside the uterus. "The mechanism underlying the role of IL-3 in abortion remains to be determined." (PMID 30893922, 2019).
acute liver failure (1 paper, 2019). Rapid deterioration of liver function causing encephalopathy and coagulopathy. "CCL11 (Eotaxin) was selectively increased in biliary atresia patients, while IL-3, IL-6, CXCL8 (IL-8), IL-9, IL-16, MIF, CCL4 (MIP-1 β), and CXCL1 (GRO-α), were increased in both biliary atresia and acute liver failure." (PMID 30740106, 2019).
acute lung injury (1 paper, 2018). A condition of lung damage that is characterized by bilateral pulmonary infiltrates (pulmonary edema) rich in neutrophils, and in the absence of clinical heart failure. "However, the effect of IL-3 in acute lung injury (ALI), an acute inflammatory disease, is unclear." (PMID 30373540, 2018).
acute pneumonia (1 paper, 2017). "The knocking in of Csf2 and Il3 was shown to increase the susceptibility of S. aureus in the context of acute pneumonia." (PMID 28523002, 2017).
acute sinusitis (1 paper, 2024). "IL-1β and TNF-α play a major role in the progression of acute sinusitis and that IL-3 dominates the cytokine profile in chronic sinusitis—leading to the coordinating effects of a variety of inflammatory cells." (PMID 38248349, 2024).
agranulocytosis (1 paper, 2025). "The PPI and KEGG enrichment pathway analyses demonstrated that clozapine induces agranulocytosis by modulating the hematopoietic cell lineage and JAK–STAT signaling pathways via interleukin‐3 (IL3), IL6, IL2 receptor subunit alpha (IL2RA), and granulocyte colony‐stimulating factor." (PMID 39776289, 2025).
amyloid (1 paper, 2022). "We showed that CSF IL-3 were associated with reduced amyloid pathology, implying that CSF IL-3 may be a key molecule linking the relationship between astrocyte and AD pathology." (PMID 36578067, 2022). "Preclinical work using mice models has shown that IL-3 can prevent neuronal death induced by amyloid pathology and can attenuate tau-related pathology." (PMID 36578067, 2022).
aplastic anemia (1 paper, 2017). Anemia resulting from bone marrow failure (aplastic or hypoplastic bone marrow). "IL3 is known to potentially support the proliferation and expansion of early myeloid progenitors leading to bone marrow reconstitution, aplastic anemia and hematopoietic recovery following chemotherapy." (PMID 28793897, 2017).
arbovirus infection (1 paper, 2021). A viral infection that is transmitted by an arthropod. "Soluble serum (IL-22, RANTES, Eotaxin) and CSF (IL-8, EGF, IL-3) mediators may discriminate putative risks for neurological complications following arbovirus infections." (PMID 33776990, 2021). "Besides EGF, IL-3 may also exert a protective role against brain damage in arbovirus infection, since IL-3 CSF levels were more than 25-folds higher than in serum, and few weak correlations were observed with other CSF molecules." (PMID 33776990, 2021).
Arrhythmia (1 paper, 2016). Any cardiac rhythm other than the normal sinus rhythm. "In spontaneously contracting cultured cardiac myocytes, perfusion with IL-3 induced arrhythmias resulting in a complete cessation of spontaneous contractions and a severe loss of myocyte inotropy; the effects were concentration-dependent and reversible." (PMID 27781209, 2016).
atopic dermatitis (1 paper, 2023). "The enrichment of the immune pathways was also high in atopic dermatitis or psoriasis, but the IL-3/IL-5/GM-CSF and IL-4/IL-13 signaling was highest in HS lesional skin." (PMID 38069342, 2023).
atrophic gastritis (1 paper, 2020). "In superficial gastritis and atrophic gastritis, the expression levels of chemokines/interleukins are relatively the same (IL14, CXCL14, and CCL28 had higher expression levels; IL3, CCL26, IL31, etc., had lower expression levels), only with a slight difference." (PMID 33426088, 2020).
breast tumor (1 paper, 2022). "This novel effector mechanism is mediated by tumor-infiltrating Th2 cells releasing IL-3, IL-5, and GM-CSF, which bind to a shared receptor on breast tumor cells." (PMID 35657353, 2022). "Th2 cells directly blocked breast carcinogenesis by secreting IL-3, IL-5, and GM-CSF, which signaled to their common receptor expressed on breast tumor cells." (PMID 35657353, 2022). "IL-3 and GM-CSF receptor genes (IL3RA, CSF2RA, and CSF2RB) were expressed in human normal mammary epithelial and breast tumor cells at markedly higher levels compared with TSLP receptor (CRLF2)." (PMID 35657353, 2022).
Cachexia (1 paper, 2022). Severe weight loss, wasting of muscle, loss of appetite, and general debility related to a chronic disease. "Muscle TFR1 downregulation was further confirmed in two different murine cachexia models, namely, LLC (Lewis Lung Carcinoma) and BaF3 (murine interleukin 3‐dependent pro‐B cell line) (Fig EV2F–K)." (PMID 35199910, 2022).
Chagas disease (1 paper, 2018). A parasitic infection caused by Trypanosoma cruzi. "In summary, the restriction of B cell development during experimental Chagas disease was accompanied by a loss in stromal cell integrity and reduction of stromal cell-derived IL-3, GM-CSF, and IL-7 and a reduction of SCF expression on stromal surface." (PMID 30619242, 2018).
chorioamnionitis (1 paper, 2025). A morphologic finding indicating inflammation of the fetal sac membranes. "We found a significant correlation between the presence of chorioamnionitis and the IL3 value of preterms (p = 0.001)." (PMID 40295408, 2025). "Although the difference in IL3 levels is not statistically relevant (likely due to the small sample size), it suggests a potential relationship between maternal chorioamnionitis, neonatal inflammatory response, and NEC development." (PMID 40295408, 2025). "Newborns of mothers with chorioamnionitis had significantly higher IL3 levels compared to those whose mothers did not have chorioamnionitis (p = 0.044)." (PMID 40295408, 2025). "The absence of a direct relationship between chorioamnionitis and NEC, despite the relationship between chorioamnionitis and elevated IL3 levels, highlights the complex multifactorial nature of NEC pathogenesis." (PMID 40295408, 2025).
cryptococcosis (1 paper, 2024). An acute or chronic, localized or disseminated infection by Cryptococcus neoformans. "We incubated PBMCs from healthy controls with 10 ng/mL of GM-CSF or IL-3 in the presence of 10% of plasma from healthy individuals or from the 30 HIV-negative patients with cryptococcosis." (PMID 39008214, 2024).
delirium (1 paper, 2013). A disorder characterized by confusion; inattentiveness; disorientation; illusions; hallucinations; agitation; and in some instances autonomic nervous system overactivity. "Patients who developed postoperative delirium were less likely to have detectable levels of IL-3 (44.7% vs. 17.4%, P=0.05)." (PMID 24093540, 2013).
demyelinating disease (1 paper, 2025). A broad group of disorders that affect the myelin sheaths that cover the neurons. "Conversely, the inhibitory roles of IL-3 and IL-21 highlight their contribution to the inflammatory milieu, further linking glial-peripheral immune crosstalk to the progression of demyelinating diseases." (PMID 40399986, 2025).
desmoid tumor (1 paper, 2015). A desmoid tumor (DT) is a benign, locally invasive soft tissue tumor associated with a high recurrence rate but with no metastatic potential. "The V530I mutant from patient 8 is known to show IL3 independent growth in FDC-P1 cells and seems to have an effect on imatinib sensitivity in desmoid tumors." (PMID 25894969, 2015).
dilatation (1 paper, 2022). "Collectively, these results are consistent in showing that the combined cardiac overexpression of IL9, IL3, IL4, IL13, and IL15 during the chronic phase of CVB3-induced VM can significantly improve the outcome of cardiac disease, reducing cardiac dilatation and dysfunction." (PMID 35508525, 2022).
encephalitis (1 paper, 2023). An acute inflammatory process affecting the brain parenchyma. "In encephalitis patients, the levels of inflammatory cytokines, such as IFN-b, IFN-g, IL-3, and TNF-a, were directly correlated with levels of the previously listed bacteria and could reflect disease severity." (PMID 38259358, 2023).